IL6 (interleukin 6)
Diseases named in the same sentence as IL6 in open-access papers (continued):
Sharing a sentence is not in itself a finding about the gene and the disease.
endometrial cancer (continued). "C-peptide, insulin, C-reactive protein, leptin, IL-1Ralpha, and IL-6 decreased significantly, while SHBG, IGFBP1, and adiponectin increased significantly in weight-loss interventions in endometrial cancer." (PMID 31440472, 2019). "In endometrial cancer, E2 has been shown to induce IL6 production through cooperation between ERα and nuclear factor-kappa B." (PMID 29970138, 2018). "Other evidence illustrated that IL6 is up-regulated by E2 through the estrogen receptor pathway in endometrial cancer, suggesting that IL6 is an important estrogen target gene." (PMID 29970138, 2018). "Work in endometrial cancer has demonstrated that tumor cell production of IL-6 leads to upregulation of aromatase in stromal cells, creating a cycle that drives tumor proliferation." (PMID 29898754, 2018). "In an orthotopic nude endometrial carcinoma model, IL6 promoted tumour growth, while targeted inhibition of the IL6 receptor dramatically reduced tumour growth in HEC1A cell-derived subcutaneous xenografts in immune-deficient mice." (PMID 28186993, 2017). "Autocrine IL-6 signaling has also been found to promote growth, metastasis and chemoresistance in a variety of tumors, including breast, ovarian and endometrial cancers." (PMID 25609203, 2015). "For example, increased IL-6 concentrations have been reported in patients with endometrial carcinoma, and more recently, IL-6, CRP, and IL1Ra were reported to be significantly associated with endometrial cancer risk in a prospective study." (PMID 23819063, 2013). "Notably, IL‐6 enhances endometrial cancer cell proliferation via the ERK‐NFκB signaling pathway, while IL‐8 facilitates immune cell recruitment to the TME." (PMID 40922069, 2025). "Using qRT‐PCR analysis, endometrial cancer tissues (n = 39) exhibited higher expression levels of adiponectin, leptin, IL6, TNFα, and their receptors, IL6R and TNFRSF1A/B, compared to the calibrator sample, which consisted of five pooled benign endometrial control samples." (PMID 40642843, 2025). "The increased mRNA expression of adiponectin (ADIPOQ), leptin, IL6, and TNFα in endometrial cancer tissue highlights an enhanced inflammatory and metabolic state within the tumor microenvironment, which may drive cancer progression." (PMID 40642843, 2025). "In endometrial cancer, high levels of Interleukin-6 are secreted by CAFs." (PMID 41228294, 2025). "IL-6, as a multifunctional factor, promotes endometrial cancer, not only in relation to JAK/STAT3." (PMID 39188680, 2024). "Although the relationship between IL6 and TNFα levels and endometrial cancer appears contentious in the literature, both cytokines have been shown to promote endometrial cancer progression by facilitating cell growth, metastasis, and epithelial-mesenchymal transition (EMT)." (PMID 38339282, 2024). "Interestingly, the PI3K/AKT/mTOR pathway mediates signaling from leptin and IL-6, which, in our study, have been found to be significantly elevated in type I endometrial cancer patients and positively correlated with tumor prognostic factors." (PMID 35053431, 2022). "Strikingly, the correlation between ROS and IL-6, and between ROS and stage of disease, has been found in both type I and II endometrial cancer patients, thus substantiating the evidence showing that metastatic disease and chronic inflammation are associated with ROS independently from adiposity." (PMID 35053431, 2022). "In the present study, we aimed to investigate the correlation between BMI, leptin, the proinflammatory cytokines IL-6 and TNFα, reactive oxygen species (ROS), and the traditional prognostic factors T, G, N and M status among type I endometrioid and type II endometrial cancer patients." (PMID 35053431, 2022). "Furthermore, mRNA expression of IL-6, IL-8, and IL-17 in the endometrial microenvironment is significantly different between women with endometrial cancer vs. benign uterine lesions." (PMID 36303679, 2022).
endometrial cancer (continued). "IL-6 has been reported to promote endometrial cancer cell migration in various studies." (PMID 34951691, 2022). "In addition, YAP can interact with the promoter of IL-6, increasing the transcription level of IL-6, which is significant for the tumorigenesis of endometrial cancer cell lines." (PMID 36226249, 2022). "Consistently with our findings, another paper reported that endometrial cancer patients had increased levels of oxidative stress markers, in comparison to controls, and that they were associated with increased values of circulating TNF-α, IL-6, and CRP." (PMID 35053431, 2022). "In gene knockout experiment with small interfering-YAP (si-YAP), addition of si-YAP suppressed proliferation of endometrial cancer cells and decreased the expression of IL-6 and IL-11, which proves that YAP induces IL-6 and IL-11 which in turn promotes cell proliferation." (PMID 34951691, 2022). "This indicated that CAF stimulates endometrial cancer proliferation via IL-6 signalling." (PMID 34951691, 2022). "We evaluated the information provided in articles published in English using a combination of keywords relevant to the proper adipokines, angiogenic growth factors (VEGF, FGF and IGF-1), inflammatory cytokines (TNFα, IL-6, IL-1β and IL-8) and endometrial cancer." (PMID 33799622, 2021). "Targeted inhibition of YAP by VP inhibited the binding between YAP and the IL-6 promoter, and downregulated IL-6 and IL-11 in endometrial cancer cells, resulting in lower proliferation rates, increased sensitivity to adriamycin, and 45.36% decrease in tumor weight in the treated mice." (PMID 33178014, 2020). "In addition, estrogen can promote the expression of IL-6 in endometrial cancer cells by binding to GPER on the cell surface." (PMID 31440472, 2019). "Indeed, IL-6 has been found to be overexpressed in the stroma of endometrial cancer." (PMID 35053431, 2022). "For example, a previously reported association of circulating IL-6 concentrations with endometrial cancer risk could reflect IL-6 secretion by endometrial cancer-associated fibroblasts rather than a role of IL-6 in endometrial cancer development." (PMID 35436960, 2022). "Studies focused on endometrial carcinoma have revealed a paracrine signaling axis whereby cancer cells produce IL-6 to stimulate stromal cells to upregulate aromatase and produce estrogen, thus inducing a cycle of increased cancer cell proliferation and IL-6 production." (PMID 26884646, 2016). "Studies have demonstrated a link between obesity, endometrial cancer, and increased levels of CRP, IL-1Rα, IL-6, and tissue CD8+ cells." (PMID 38230225, 2024). "These outcomes seem to be generally universal across different ethnic groups, regarding both clinical metrics (BMI, waist circumference) and endometrial cancer-related biomarkers (IGF-1, leptin, adiponectin, IL-1, IL-6) 89, 97-100." (PMID 38230225, 2024). "This study demonstrated that robotic laparoscopy for early endometrial cancer yields notably diminished postoperative levels of inflammatory and tissue damage markers, specifically hs-CRP, WBC, IL-6, and cortisol, when compared to conventional laparoscopy." (PMID 39554498, 2024). "Seventy-one articles reported that various cytokines, such as TGF-β, TNF-α, IL-6, etc., promoted EMT changes in ovarian, cervical, and endometrial cancers." (PMID 36766756, 2023). "The studies included have demonstrated a downregulation of epithelial marker E-cadherin in endometrial cancer cells by TGF-β treatment, AMF treatment, and IL-6 treatment and when treated with chemokine CCL18 and RANK/RANKL/CCL20." (PMID 36766756, 2023). "N-cadherin was over expressed when endometrial cancer cells were treated with TGF-β, IL-6, chemokines CCL18, RANK/RANKL/CCL20, and CXCR4/CXCL12." (PMID 36766756, 2023).
endometrial cancer (continued). "IL-6, Il-11, IL-31, IL-33, TNF-α, TGF-β1, SDF-1 and CXCR are involved in endometrial cancer cell growth and metastasis or involved in epithelial mesenchymal transformation (EMT) or associated with advanced disease." (PMID 34951691, 2022). "In turn, IL-6 and TNF-α induce the stromal expression of hepatocyte growth factor (HGF) which in turn stimulates endometrial cancer invasion." (PMID 34951691, 2022). "IL-6 and TGF-β1 treatments of endometrial cancer cell lines were demonstrated to affect a decrease in epithelial marker (E cadherin) and an increase in mesenchymal markers (Twist, Snail, N-cadherin)." (PMID 34951691, 2022). "The main cytokines secreted by CAFs isolated from human endometrial cancer tissue include MCP-1, CCL5, RANTES, interleukin-6, and -8 (IL-6, IL-8) VEGF, EGF, HGF, FGF-2, as well as TGFβ1 isoform." (PMID 34501347, 2021). "These are ERRFI1, IL6, PIK3R1 and SPRY2 which were found to be upregulated and YWHAZ which was found to be downregulated; Endometrial cancer has twelve genes." (PMID 34764329, 2021). "Recent evidence has shown that ADCS provoke an increase in IL6 levels, which induces the phosphorylation of JAK2/STAT316, resulting in proliferation, invasion and tumor growth in prostate and endometrial cancers." (PMID 32848147, 2020). "Additionally, PER1 overexpression in endometrial cancer cells promotes the expression of immune factors TNF-α and IL-6, while upregulating immune checkpoints programmed death-1 (PD-1)/programmed death-ligand 1 (PD-L1)." (PMID 41451215, 2025). "This study demonstrated that robotic laparoscopy, used in early endometrial cancer treatment, leads to a reduced inflammatory response, less tissue damage, and lower stress levels, as evidenced by decreased levels of hs-CRP, IL-6, and cortisol, compared to conventional laparoscopy." (PMID 39554498, 2024). "The reciprocal relationship between IL-6 and E2 through aromatase activity has been established in endometrial cancer, but not in SSc dermal fibrosis." (PMID 39000334, 2024). "We found that BMI, leptin, IL-6, and reactive oxygen species correlated with T, N, and M status in type I, but not in type II endometrial cancers." (PMID 35053431, 2022). "We measured CA125, IL-6, and TNF-α levels to confirm the development of endometrial cancer." (PMID 35371322, 2022). "The plasma levels of CA125, IL-6, and TNF-α increased in the endometrial cancer group." (PMID 35371322, 2022). "Among type II endometrial cancer patients, BMI and leptin did not correlate with any of the prognostic parameters, whereas there was a positive correlation between IL-6 and the presence of distant metastases." (PMID 35053431, 2022). "Among the type II endometrial cancer patients, BMI and leptin did not correlate with any of the prognostic parameters, whereas a positive correlation between IL-6 and M status/stage was found." (PMID 35053431, 2022). "This study showed that robotic hysterectomy in an ERAS program in early endometrial cancer resulted in a significantly lower postoperative response in inflammatory, immunological and tissue damage factors including hs-CRP, WBC, IL-6, cortisol and CK as compared with abdominal hysterectomy." (PMID 32350297, 2020). "An additional study confirmed that IL6 up-regulate the aromatase level and E2 concentration in stromal cells but not in endometrial cancer cells." (PMID 29970138, 2018). "Whether secretion of growth factors (TGFβ, GAS6, FGF5 and HGF), cytokines and chemokines (IL-6, CXCL9) from CAFs,32 may affect aggressiveness and thereby associate with recurrence of endometrial cancer, is not known and could be investigated in future studies." (PMID 37146405, 2023). "In the type II endometrial cancer patients, we did not observe any correlations between oxidative stress markers, BMI, or leptin, while we demonstrated a significant linear relationship between ROS and IL-6." (PMID 35053431, 2022).
endometrial cancer (continued). "Studies of the association between the pro‐inflammatory cytokine C‐reactive protein (CRP) with endometrial cancer incidence have been mixed, and meta‐analyses of tumor necrosis factor alpha (TNF‐α) and interleukin 6 (IL‐6) have not demonstrated an association with endometrial cancer risk." (PMID 35174651, 2022). "Moreover, adipose tissue is well recognized as an active endocrine-immune organ that produces adipokines and proinflammatory mediators, mainly the inflammatory cytokines interleukin (IL)-6 and tumor necrosis factor-alpha (TNF-α), which can promote the development of endometrial cancer." (PMID 35053431, 2022). "This study examined a set of six markers, namely, adiponectin, leptin, IL6, TNFα, IGF1, and IGF2 and compared them between fifty age-matched endometrial cancer patients (study group) and non-cancer patients with benign gynaecological conditions (control group)." (PMID 38339282, 2024).
Peri-Implantitis (72 papers, 2014 to 2026). An inflammatory process with loss of supporting bone in the tissues surrounding functioning DENTAL IMPLANTS. "Further research has indicated that pro-inflammatory mediators associated with peri-implantitis include interleukin-1 beta (IL-1β), IL-6, IL-17, and tumor necrosis factor-alpha (TNF-α)." (PMID 39555067, 2024). "Regarding dental implants, a systematic review has reported that the central cytokines associated with peri-implantitis were IL-1β, IL-6, IL-17, TNF-α, RANK, and RANKL." (PMID 38614881, 2024). "Results showed that clinically stable treatment outcomes of peri-implantitis are associated with lower levels of putative pathogens total bacterial load and with reduction of IL-1β, IL-6, and VEGF levels in PICF." (PMID 31817894, 2019). "TNF-α, IL-1, and IL-6 have been identified as the most essential pro-inflammatory cytokine biomarkers and are strongly linked to the onset, development, and clinical consequences of peri-implantitis." (PMID 36015175, 2022). "Additionally, these clinical indexes were also associated with cytokine levels in peri-implantitis in this study, which showed that IL-1β, IL-6, IL-17A, VEGF, CXCL2, and G-CSF had a positive correlation with these three clinical indexes." (PMID 36233685, 2022). "Pro-inflammatory cytokines such as interleukin-1β, interleukin-6, and tumor necrosis factor can impair osteogenic differentiation and promote osteoclast activation, leading to bone resorption in peri-implantitis." (PMID 41535819, 2026). "In univariate logistic regression analyses, both IL-1β and IL-6 were suggested as potential predictors of peri-implant mucositis and peri-implantitis (all p < 0.05)." (PMID 41877785, 2026). "In peri-implantitis, IL-6, IL-1β, TNF-α, MMP-8, and their genetic variations appear to be the most important cytokines not only in pathogenesis but also in their potential diagnostic capabilities." (PMID 41172495, 2025). "Cytokine levels in PICF were markedly elevated in peri-implantitis cases: IL-6 (235.56 ± 56.34 pg/mL vs. 22.88 ± 8.06 pg/mL), IL-10 (73.13 ± 15.11 pg/mL vs. 13.13 ± 4.25 pg/mL), and TNF-α (148.94 ± 53.99 pg/mL vs. 8.31 ± 2.89 pg/mL)." (PMID 40959363, 2025). "Higher levels of proinflammatory cytokines (interleukin (IL)-1β and IL-6) were observed in individuals with peri-implantitis compared to healthy implants." (PMID 38541894, 2024). "Specific immunity in peri-implantitis is characterized by elevated levels of pro-inflammatory cytokines such as IL-1β, IL-6, IL-17, and TNF-α, secreted by activated T cells and other immune cells." (PMID 39555067, 2024). "In the group of peri-implantitis who had a high score in stress level assessment scales, significantly higher IL-1β, IL-6, sAA expression levels were observed (p < 0.001)." (PMID 38691206, 2024). "Observe the effects of treatment on clinical parameters indicative of mucositis or peri-implantitis (Δ PD; Δ PI; Δ BoP) and/or immunological parameters (Δ IL-1β; Δ IL-6; Δ IL-8; TNF-α)." (PMID 38686378, 2024). "A case-control study involving the collection of tissue biopsies from volunteers diagnosed with peri-implantitis and healthy controls revealed elevated levels of gene expression of AhR and IL-6 in peri-implantitis tissues." (PMID 39575260, 2024). "As inflammatory biomarkers, the variations of IL-1β, IL-6, and TNF-α are the most commonly studied functional polymorphisms for peri-implantitis and peri-implant bone loss." (PMID 36643585, 2023). "The complex formed with sIL-6R in peri-implantitis lesions and IL-6 produced from Clys-stimulated HGFs exacerbates the inflammatory response to produce IL-8, IL-6, and pro-MMP-1 and activate the gp130/STAT3 pathway." (PMID 36834667, 2023). "Higher levels of IL-6 and lower levels of IL-10 were found in peri-implantitis individuals in comparison to mucositis and healthy individuals." (PMID 37355561, 2023).